TBX5 (T-box transcription factor 5)
Description:
DNA-binding protein that regulates the transcription of several genes and is involved in heart development and limb pattern formation. Binds to the core DNA motif of NPPA promoter.
Synonyms: HOS
Tractability: No criterion of Open Targets' tractability assessment is met for any kind of drug.
Target class: Transcription factor
Gene: Protein-coding gene on chromosome 12 (114,353,911 to 114,409,103, reverse strand). Ensembl gene ENSG00000089225.
Subcellular location: Nucleus; Cytoplasm
Subcellular location (Human Protein Atlas): Nucleoplasm
Pathways (Reactome):
Developmental Biology: Cardiogenesis
Gene expression (Transcription): YAP1- and WWTR1 (TAZ)-stimulated gene expression
Muscle contraction: Physiological factors
Gene Ontology:
Molecular function: DNA binding; DNA-binding transcription factor activity; DNA-binding transcription factor activity, RNA polymerase II-specific; protein binding; RNA polymerase II cis-regulatory region sequence-specific DNA binding; RNA polymerase II-specific DNA-binding transcription factor binding; sequence-specific DNA binding; DNA-binding transcription activator activity, RNA polymerase II-specific; RNA polymerase II transcription regulatory region sequence-specific DNA binding
Biological process: cell-cell signaling; embryonic forelimb morphogenesis; embryonic limb morphogenesis; forelimb morphogenesis; heart development; negative regulation of cardiac muscle cell proliferation; negative regulation of cell migration; negative regulation of cell population proliferation; pericardium development; positive regulation of cardioblast differentiation; positive regulation of DNA-templated transcription; positive regulation of transcription by RNA polymerase II; atrioventricular bundle cell differentiation; atrioventricular node cell development; atrioventricular node cell fate commitment; bundle of His cell to Purkinje myocyte communication by electrical coupling; bundle of His development; cardiac left ventricle formation; cell fate specification; cell migration involved in coronary vasculogenesis; negative regulation of epithelial to mesenchymal transition; pattern specification process; positive regulation of cardiac conduction; positive regulation of cell communication by electrical coupling involved in cardiac conduction; positive regulation of gap junction assembly; and 6 more
Cellular component: cytoplasm; nucleus; protein-containing complex; protein-DNA complex; chromatin; nucleoplasm; transcription regulator complex
Genetic constraint (gnomAD): Loss-of-function variants: 8 observed, 54 expected, observed/expected ratio (o/e) 0.15, 90% interval 0.086 to 0.27. The upper end of that interval is the gene's LOEUF score, 0.27, which puts it in group 1 of 6, group 1 being the genes least tolerant of losing a copy. Missense variants: 589 observed, 707.2 expected, observed/expected ratio (o/e) 0.83, 90% interval 0.78 to 0.89. Synonymous variants: 302 observed, 282.25 expected, observed/expected ratio (o/e) 1.07, 90% interval 0.97 to 1.18.
Gene-disease validity (ClinGen):
ClinGen rates the evidence that TBX5 causes each of these diseases.
Holt-Oram syndrome (autosomal dominant): Definitive. Holt-Oram syndrome (HOS) is the most common form of heart-hand syndrome and is characterized by skeletal abnormalities of the upper limbs and mild-to-severe congenital cardiac defects.
Homologues: Orthologues: chimpanzee TBX5 (99% identical), macaque TBX5 (99% identical), pig TBX5 (98% identical), guinea pig TBX5 (97% identical), dog TBX5 (97% identical), mouse Tbx5 (96% identical), rat Tbx5 (96% identical), rabbit TBX5 (96% identical), tropical clawed frog tbx5 (81% identical), zebrafish tbx5a (70% identical), Drosophila melanogaster mid (24% identical), Drosophila melanogaster H15 (24% identical), and 9 more. Paralogues in human: TBX4 (54% identical), MGA (33% identical), TBX3 (31% identical), TBX2 (30% identical), TBX15 (30% identical), TBX18 (28% identical), TBX1 (28% identical), TBX20 (27% identical), EOMES (26% identical), TBR1 (26% identical), TBX10 (26% identical), TBX22 (25% identical), and 4 more.
Diseases named in the same sentence as TBX5 in open-access papers:
TBX5 is named in the same sentence as 150 diseases in open-access papers, as found by Europe PMC text mining. Sharing a sentence is not in itself a finding about the gene and the disease. The quoted sentences say what the papers report.
Holt-Oram syndrome (123 papers, 2007 to 2026). "TBX5 is a transcription factor gene that causes VSDs in Holt–Oram syndrome from haploinsufficiency in humans and mice." (PMID 41461901, 2026). "TBX5 is highly expressed in the forelimb buds and the developing heart, and mutations in this gene cause Holt-Oram syndrome." (PMID 40917916, 2025). "TBX5 is a gene known to be involved in cardiovascular development in humans, and TBX5 mutations result in cardiac malformations as seen in Holt‐Oram syndrome." (PMID 40161031, 2025). "GATA4 are associated with various septal defects, while mutations in TBX5 cause Holt-Oram syndrome, a condition characterized by upper limb deformities and, most notably, ASDs." (PMID 41049289, 2025). "Specifically, Holt‐Oram syndrome is caused by missense mutations in the TBX5 gene, resulting mostly in a loss of function of the TBX5 protein, leading to upper limb and cardiac malformations, including MV abnormalities such as MVP." (PMID 40161031, 2025). "For our patient, Holt and Oram syndrome was confirmed due to the presence of the TBX5 gene mutation, which allowed other differential diagnoses of this syndrome to be ruled out." (PMID 39230761, 2024). "A genetic consultation was requested, and a genetic study was carried out, which revealed a mutation in the TBX5 gene, confirming Holt–Oram syndrome." (PMID 39230761, 2024). "It is well established that a reduction in the dosage of TBX5 impairs heart development and heterozygous mutations in the TBX5 gene causing Holt–Oram syndrome and resulting in septal defects." (PMID 39596866, 2024). "Holt–Oram syndrome is an autosomal dominant condition caused by mutations in the TBX5 gene, which affect both limb and heart development." (PMID 39596866, 2024). "As one of the first identified monogenic etiologies of familial congenital heart disease, the TBX5 dominant mutation has been reported in Holt-Oram syndrome, known for septation and forelimb defects." (PMID 38525280, 2024). "Holt-Oram syndrome is partially caused by variants in the TBX5 gene, and GWAS studies on AF have shown several significant loci with nearest genes known to be important for heart development and causal for CHD, such as NKX2-5, GATA4, GJA1, and GJA5." (PMID 38454350, 2024). "Holt–Oram syndrome is a rare genetic disorder caused by a mutation in the TBX5 gene, combining skeletal and cardiac malformations." (PMID 39230761, 2024). "For example, TBX1 and TBX5 haploid insufficiency respectively causes DiGeorge syndrome charactered as pharyngeal, cardiac, thymic, craniofacial hypoplasia and Holt–Oram syndrome (HOS) charactered as cardiovascular malformations, skeletal malformations." (PMID 38965548, 2024). "Holt-Oram syndrome involves TBX5 mutations and is associated with dysrhythmias and limb malformations." (PMID 39156437, 2024). "TBX5 haploinsufficiency has been linked to Holt-Oram Syndrome, and part of the patients have been reported to display coronary artery abnormality (Liberatore, Searcy-Schrick & Yutzey, 2000; Steimle & Moskowitz, 2017)." (PMID 38525280, 2024). "Pathogenic variants in TBX5 are a known cause of Holt–Oram syndrome featured by CHDs and forelimb maldevelopment." (PMID 36675070, 2023). "A landmark study in 2012 showed that a mutation in a TBX5 RE was associated with a case of isolated congenital heart disease, atypical for TBX5 loss-of-function mutations and Holt–Oram syndrome." (PMID 38201209, 2023). "Select putative gain-of-function TBX5 alleles cause atypical Holt-Oram syndrome with mild skeletal defects and paroxysmal atrial fibrillation." (PMID 37125615, 2023). "TBX5 is transcription factor which is involved in the development of the limbs and heart, and mutations in TBX5 have been shown to cause Holt–Oram syndrome." (PMID 38201209, 2023).
Holt-Oram syndrome (continued). "For example, traditional linkage analysis in patients with Holt-Oram syndrome implicated the gene for the TBX5 transcription factor, which harbors variants predicted to disrupt protein structure and/or function in affected patients." (PMID 37096669, 2023). "Patients with dominant mutations in TBX5 are characterized by Holt-Oram syndrome, and show defects of the cardiac septum, cardiac conduction system, and the anterior forelimb." (PMID 38019868, 2023). "A pathogenic variant in the 5th exon of TBX5, which contains the T-box domain, called p.G125R;c373G>A, was identified in a Dutch family presenting with atypical Holt-Oram syndrome and paroxysmal AF." (PMID 37194974, 2023). "In 1997, two separate groups confirmed that mutations in TBX5 were causative for Holt-Oram syndrome, resulting in predicted instances of haploinsufficiency." (PMID 37125615, 2023). "TBX5 haploinsufficiency causes Holt-Oram syndrome, which is characterized by congenital arm/hand and heart defects and by cardiac conduction system abnormalities." (PMID 37194974, 2023). "TBX5, as the causative gene in Holt-Oram syndrome, provides another potent example for joint expression in different LPM descendants." (PMID 37125615, 2023). "Holt–Oram syndrome has been typically associated with mutations in TBX5, even though new evidence has shown that KLF-13 plays a pathogenic role, as researchers have identified KLF-13 as a genetic modifier for TBX5." (PMID 36836777, 2023). "Haploinsufficiency of TBX5 is known to cause Holt-Oram syndrome in human patients, which is characterized in part by skeletal malformations." (PMID 37749158, 2023). "Two individuals presented with LVNC, and genetic testing identified putative loss of function variants in TBX5 with subsequent clinical review confirming a diagnosis of Holt-Oram syndrome." (PMID 36578016, 2022). "The pathogenic missense variant p.G125R in TBX5 (T-box transcription factor 5) causes Holt–Oram syndrome (also known as hand–heart syndrome) and early onset of atrial fibrillation." (PMID 35113653, 2022). "Mutations within the TBX3 and TBX5 genes provide an embryologic basis for the prevalence of atrial and/or ventricular septal defects in patients with Holt-Oram syndrome." (PMID 35698674, 2022). "Holt-Oram syndrome is a rare autosomal dominant disorder which occurs because of mutations in the TBX5 genes." (PMID 35698674, 2022). "A TBX5 gene mutation has been identified in approximately 74% of individuals affected with Holt-Oram syndrome." (PMID 40041224, 2022). "Limb defects and atrioventricular septal defects, caused by altered pSHF development, are both a facet of the phenotypic spectrum observed in Holt–Oram syndrome in human patients with TBX5 mutations." (PMID 34643182, 2021). "Monoallelic variants of the T-Box transcription factor 5 (TBX5) are responsible for the Holt-Oram syndrome (MIM 142900), which is characterized by skeletal impairments of the upper limbs as well as congenital heart defects." (PMID 34149817, 2021). "In particular, Tbx5 has been extensively studied over the past decade because its mutation is associated with cardiac and limb defects observed in Holt-Oram syndrome." (PMID 34276786, 2021). "Non-coding mutations in TBX5 cardiac enhancers were found to cause a large number of CHDs associated with TBX5 dysfunction, effectively decoupling the heart, and hand phenotype of Holt-Oram syndrome." (PMID 33585489, 2021). "Zebrafish tbx5 mutants prominently recapitulate the joint cardiac and forelimb defects found in human TBX5-associated Holt–Oram syndrome patients, the original paradigm of so-called heart-hand anomalies." (PMID 33578943, 2021). "Distal cis-regulatory elements have been identified in TBX5, of which variants are responsible for Holt-Oram syndrome." (PMID 33585486, 2021).
Holt-Oram syndrome (continued). "For example, tbx5a, whose human ortholog TBX5 causes the Holt–Oram syndrome characterized by congenital heart malformation due to variable atrial and ventricular septal defects as well as heart conduction defects." (PMID 34557935, 2021). "TBX5 has been linked to Holt-Oram syndrome, with congenital heart defect (CHD)and atrial fibrillation (AF) being two major cardiac phenotypes." (PMID 33306779, 2020). "Mutations in the T-box transcription factor TBX5 cause Holt–Oram Syndrome (HOS), a syndrome characterized by multiple developmental abnormalities." (PMID 33158164, 2020). "TBX5 mutations lead to Holt-Oram syndrome, which is characterized by forelimb musculo-skeletal defects." (PMID 31063509, 2019). "Mutations in TBX5 gene cause Holt-Oram syndrome (HOS), which is characterized by congenital heart defects and upper limb abnormalities." (PMID 31775637, 2019). "Conversely, TBX5 plays a synergistic role with MEF-2C in the early phases of cardiomyocyte development and differentiation, and mutations in TBX5 are associated with Holt-Oram syndrome which features massive heart and forelimb abnormalities." (PMID 31105874, 2019). "To do this, we knocked down Tbx5, the causative gene for Holt-Oram syndrome, which is associated with left-sided ventricular heart malformation including hypoplastic left heart syndrome in humans and mice." (PMID 30087351, 2018). "Holt-Oram syndrome is a dominant disorder caused by a single-allele mutation of TBX5 and is characterized by hypoplasia of the forelimb, abnormalities in the thumb, and atrial and/or ventricular septal defects." (PMID 30587117, 2018). "Mutations of the TBX5 gene caused Holt-Oram syndrome (HOS), which is a rare syndrome and is characterized by a malformation of the upper limbs and variable cardiac defects." (PMID 30143665, 2018). "This possibility is also supported by the positive correlation observed between cardiac defects involved in Holt–Oram syndrome (caused by TBX5 mutations) with the spatial expression of Tbx534." (PMID 30464173, 2018). "In humans, mutation of just one copy of TBX5 is associated with Holt-Oram syndrome, in which heart and forearm defects occur in 1 in 100,000 live births." (PMID 30532148, 2018). "It is well known that the mutations in TBX5 gene coding regions have a role in syndromic CHD such as Holt-Oram syndrome." (PMID 28761722, 2017). "In the genetic era, mutations in TBX5 were amongst the first to be linked to syndromic CHD cases by linkage analysis of patients with Holt-Oram syndrome (OMIM #142900)." (PMID 28469241, 2017). "Holt-Oram Syndrome (HOS) is a serious condition caused by haploinsufficiency of the transcription factor Tbx5." (PMID 28133602, 2016). "Genetically, single gene causes of CHDs such as TBX5 mutations in Holt-Oram-Syndrome or mutations in the cardiac differentiation factor NKX2.530, 31 explain a relatively small proportion of all known cases." (PMID 27618959, 2016). "Mutations in the T-box transcription factor TBX5 account for more than 70% of patients with Holt-Oram Syndrome (HOS), which is characterized by ASDs, ventricular septal defects (VSDs) and cardiac conduction defects." (PMID 29367567, 2016). "In some patients with Holt-Oram syndrome and AF, the disease is caused by Tbx5 mutations that create a premature termination codon, which is predicted to result in haploinsufficiency." (PMID 26221584, 2015). "Mutations in TBX5 cause Holt–Oram syndrome (OMIM #142900), a syndrome distinguished by upper limb defects and heart defects—primarily septal and conduction defects." (PMID 23934094, 2014). "Mutations in human TBX5 cause Holt–Oram syndrome (HOS; OMIM#142900), an autosomal-dominant ‘heart–hand’ condition characterized by heart and upper limb malformations." (PMID 24759614, 2014). "Mutations in human TBX5 cause Holt–Oram syndrome, a condition characterized by heart and upper limb malformations." (PMID 24759614, 2014).
Holt-Oram syndrome (continued). "Holt-Oram syndrome is caused by mutations in TBX5, a T-box transcription factor gene family member coded for by a gene on chromosome 12q2." (PMID 23984174, 2013). "Mutation of TBX5 is the main cause of Holt-Oram syndrome, a hereditary disease characterized by forelimb and cardiac congenital defects such as atrial and ventricular septal defect." (PMID 23717681, 2013). "Holt-Oram syndrome is an autosomal dominant disorder which is caused by mutations of TBX5 and is characterised by cardiac and skeletal abnormalities." (PMID 23984174, 2013). "Dysmorphogenesis and multiple organ defects are well known in zebrafish (Danio rerio) embryos with T-box transcription factor 5 (tbx5) deficiencies, mimicking human Holt-Oram syndrome." (PMID 22776023, 2012). "The first genetic etiology for atrial septal defects was the disovery that mutations in the transcription factor, TBX5, are a cause of septation defects in the setting of Holt-Oram syndrome, which is characterized by cardiac and upper limb malformations." (PMID 22589735, 2012). "The tbx5 mutation in human causes Holt-Oram syndrome, an autosomal dominant condition characterized by a familial history of congenital heart defects and preaxial radial upper-limb defects." (PMID 21982178, 2011). "In humans, TBX5 mutationslead to Holt-Oram syndrome, which is characterised by forelimb musculo-skeletaldefects." (PMID 20152185, 2010). "In human, mutations in the Tbx5 gene have been associated with Holt-Oram syndrome, which is characterized by developmental anomalies in the heart and forelimbs." (PMID 20219112, 2010). "In one instance (OX2084, TBX5 mutation) a tentative diagnosis of Holt–Oram syndrome (MIM 142900) had been made, but an electrocardiogram (ECG) and echocardiogram were normal, and genetic testing was not arranged." (PMID 19429598, 2009). "Holt-Oram syndrome (HOS) is an autosomal-dominantly inherited disorder caused by mutations in the gene coding for the T-box transcription factor TBX5, which is located on chromosome 12q24." (PMID 18828908, 2008). "Patients with Holt-Oram syndrome, one of the autosomal dominant human "heart-hand" disorders, are caused by mutations of tbx5." (PMID 17683539, 2007). "Nevertheless, a recent abstract describing a currently unpublished study suggests that loss of the transcription factor TBX5 (which causes Holt-Oram syndrome, including CHD phenotypes) results in epigenetic changes within the human blastula which impact upon mesoderm specification." (PMID 41002649, 2025). "About 74% of people with Holt-Oram syndrome had a TBX5 gene mutation, according to research." (PMID 39156428, 2024). "Holt-Oram syndrome occurs due to a mutation in the TBX5 gene." (PMID 39238717, 2024). "The TBX5 gene is the only one that has been linked to Holt-Oram syndrome so far." (PMID 39156428, 2024). "Moreover, the pathogenic variant (G80R) that affects TBX5 splicing performance is directly linked to the pathogenesis of Holt–Oram syndrome and featured with complete penetrance of CHDs due to significant mis-splicing of mRNA." (PMID 36675070, 2023). "For example, coding variants at TBX5 cause cardiac defects such as Holt-Oram syndrome." (PMID 37096669, 2023). "Heterozygous loss- or gain of function variants in TBX5 can cause Holt-Oram syndrome in humans, characterized by congenital heart defects and cardiac conduction anomalies, as a result of profound changes in the gene regulatory networks controlling heart development and function." (PMID 36715501, 2023). "Currently, there are more than 70 known mutations in the TBX5 gene that cause Holt-Oram syndrome." (PMID 40041224, 2022). "The only gene known to be associated with Holt-Oram syndrome is the TBX5 gene." (PMID 40041224, 2022). "For instance, the only clinical manifestation of Holt–Oram syndrome (the result of a mutation in gene TBX5) might be a size reduction or malformation of a thumb." (PMID 33673226, 2021).